CLIC3 (CLIC family member 3)
Diseases named in the same sentence as CLIC3 in open-access papers (continued):
Sharing a sentence is not in itself a finding about the gene and the disease.
idiopathic pulmonary fibrosis (2 papers, 2013 to 2018). Idiopathic pulmonary fibrosis (IPF) is a nonneoplastic pulmonary disease that is characterized by the formation of scar tissue within the lungs in the absence of any known cause. "We also report that E2 specifically down-regulated the expression of CLIC3 and RBP7 which have been associated with pathogenic mechanisms of pulmonary fibrosis." (PMID 30165855, 2018). "Compared to the normal lung tissue, the expressions of SMAD6 and CLIC3 are lower in tissues with idiopathic pulmonary fibrosis (GDS1252) and pulmonary adenocarcinoma (GDS1650 and GDS 3257)." (PMID 23741331, 2013). "By searching the GEO profile, we predict that SMAD6 and CLIC3 could be related to idiopathic pulmonary fibrosis and pulmonary adenocarcinomas." (PMID 23741331, 2013).
lung carcinoma (2 papers, 2019 to 2025). "Among them, CLIC1, CLIC3, and CLIC4 have been investigated more extensively, particularly in the context of lung cancer, inflammatory diseases, and pulmonary arterial hypertension." (PMID 41907764, 2025).
autism (1 paper, 2023). Persistent deficits in social interaction and communication and interaction as well as a markedly restricted repertoire of activity and interest as well as repetitive patterns of behavior. "Thus, whether CLIC3 is also a potential diagnostic biomarker and therapeutic target in bipolar disorder and autism is also a topic worth further exploring." (PMID 37841288, 2023).
cervical carcinoma (1 paper, 2026). A carcinoma arising from either the exocervical squamous epithelium or the endocervical glandular epithelium. "Additionally, CLIC3 was significantly upregulated in this cluster, a gene associated with HPV‐induced neoplastic cervical lesions and contributing to poor prognosis in patients with cervical carcinoma." (PMID 41362277, 2026).
clear cell renal cell carcinoma (1 paper, 2019). "Among these genes we observed CLIC3, PRAP1 and AHNAK2, which have been shown to promote cancer progression of gallbladder carcinoma, chemotherapeutic drug resistance in colorectal cancer and epithelial to mesenchymal transition in clear cell renal cell carcinoma, respectively." (PMID 30717152, 2019).
diabetes mellitus (1 paper, 2024). A metabolic disorder characterized by abnormally high blood sugar levels due to diminished production of insulin or insulin resistance/desensitization. "In diabetes mellitus, CLIC3 is significantly downregulated with a result of increased clinical complications." (PMID 39483475, 2024).
hepatocellular carcinoma (1 paper, 2022). A malignant tumor that arises from hepatocytes. "CLIC3 is a chloride intracellular channel protein the gene expression of which has been correlated with low immune infiltration of myeloid dendritic cells (DCs) and poor prognosis in hepatocellular carcinoma." (PMID 36421334, 2022).
malignant pleura mesothelioma (1 paper, 2020). "Previous studies have shown that, the gene expression of CLIC3 was significantly increased compared to healthy controls in human cancer, such as malignant pleura mesothelioma (MPM) 35-37." (PMID 32328183, 2020).
melanoma (1 paper, 2012). A malignant, usually aggressive tumor composed of atypical, neoplastic melanocytes. "Interestingly, this includes many genes that we found commonly regulated between fish and human melanoma (e.g. BCL2, WNT family members) or which became evident in the fish tumor comparisons, e.g. components of the ECM, cell cycle regulators, PLP1, and CLIC3." (PMID 22693581, 2012).
pancreatic adenocarcinoma (1 paper, 2012). "Importantly, the histoscore values for CLIC3 and phospho-Src were strongly correlated with one another in pancreatic adenocarcinoma, indicating the possibility that CLIC3 is associated with upregulated integrin signaling in vivo." (PMID 22197222, 2012).
schizophrenia (1 paper, 2023). A major psychotic disorder characterized by abnormalities in the perception or expression of reality. "In conclusion, using various bioinformatic and biological methods, this study found an immune-related hub gene of schizophrenia – CLIC3 that might be a potential diagnostic biomarker and therapeutic target for schizophrenia." (PMID 37841288, 2023). "Back to the mRNA expression data, the mRNA expression of CLIC3 was significantly decreased in the schizophrenia samples compared to the healthy controls." (PMID 37841288, 2023). "In particular, CLIC3 has potential to be a promising biomarker or therapeutic target of schizophrenia." (PMID 37841288, 2023). "A schizophrenia rat model was established to validate CLIC3 expression and found that CLIC3 levels were reduced in the model rat plasma and brains in a brain-regional dependent manner, but can be reversed by an antipsychotic drug risperidone." (PMID 37841288, 2023). "To validate above bioinformatic results, we investigated CLIC3 expression in a schizophrenia animal model." (PMID 37841288, 2023). "Of these 3 candidate groups, 1 intersection gene was acquired as the immune-related hub genes of schizophrenia, which was CLIC3." (PMID 37841288, 2023). "Nevertheless, the exact relationship between CLIC3 expression and schizophrenia-related brain regions cannot be elucidated by the present data." (PMID 37841288, 2023). "However, in-depth investigations, especially the examination of CLIC3 expression in schizophrenia patients, are still required to further verify the role of CLIC3 in schizophrenia." (PMID 37841288, 2023). "Therefore, we established a schizophrenia animal model and examined the protein expression of CLIC3 in the plasma and brain." (PMID 37841288, 2023). "On the other hand, employing a long-term schizophrenia animal model might also be an effective approach to examine the changes of CLIC3 in schizophrenia and validate our current findings." (PMID 37841288, 2023). "The expression of CLIC3 was presented in all four schizophrenia-related brain regions." (PMID 37841288, 2023). "The result showed that the CLIC3 expression was down-regulated in schizophrenia patients’ cortex." (PMID 37841288, 2023). "Finally, CLIC3 was found as an immune-related hub gene of schizophrenia by the three machine learning algorithms." (PMID 37841288, 2023). "Furthermore, we examined the protein expression of CLIC3 in rat schizophrenia rat brains." (PMID 37841288, 2023). "It should also be noted that the antipsychotic drug - risperidone also eliminated the inhibitory effects of MK-801 on CLIC3 expression in both PFC and CPu (both p < 0.05 vs. the MK-801 group), indicating that CLIC3 might be a potential therapeutic target of schizophrenia." (PMID 37841288, 2023). "Unfortunately, the exact role of CLIC3 in schizophrenia is not clear based on existing literature." (PMID 37841288, 2023).
cancer (34 papers, 2012 to 2025). A tumor composed of atypical neoplastic, often pleomorphic cells that invade other tissues. "A study of the secretome from cancer-associated fibroblasts found that CLIC3 was abundantly expressed." (PMID 41008519, 2025). "CLIC3 is highly abundant in cancer-associated fibroblasts (CAFs), where it is secreted into the extracellular matrix (ECM)." (PMID 41465326, 2025). "High expression levels of CLIC1 and CLIC3 were associated with advanced cancer stage in HCC patients." (PMID 34766585, 2021). "Since tumor proliferation is associated with tumor depth, we examined effects of CLIC3 expression on cancer cell proliferation." (PMID 32066374, 2020). "In addition, CLIC3, secreted by cancer cells or cancer-associated fibroblasts (CAFs), increases the invasiveness of cancer cells." (PMID 38245587, 2024). "CLIC3 is a multifunctional protein involved in the progression, metastasis, and therapy resistance of several cancer types." (PMID 41465326, 2025). "GZMB can inhibit the T cell proliferation, PTPRS can inhibit the production of interferon, and CLIC3 takes part in the angiogenesis and increases the invasiveness of cancer cells." (PMID 40755770, 2025). "Mechanistically, CLIC3 acts in concert with Rab25 to recycle α5β1 integrin, facilitating cancer cell invasiveness by promoting integrin’s trafficking from late endosomes to the plasma membrane." (PMID 41465326, 2025). "It was able to show sprouting angiogenesis in a more cancer-like environment and that CLIC3 was indeed a key driver for promoting ECs to form nascent vessels." (PMID 40427172, 2025). "Studies have shown that CLIC3 promotes cancer progression through its glutathione-dependent oxidoreductase activity." (PMID 37064135, 2023). "CLIC3 has been found to be expressed in human placenta and fetal membranes, osteoblasts, and various cancer cells." (PMID 37841288, 2023). "Many of these DEGs, including CGA, CDKN1A, FN1, CLIC3, and S100P, have been reported to play essential roles in cancer progression." (PMID 35521536, 2022). "It is noted that the relationship between expression level of CLIC3 and prognosis were opposite to the previous reports, although the types of cancer are different." (PMID 32066374, 2020). "In the specimens judged as “CLIC3-high”, CLIC3 protein was localized in both the plasma membrane and intracellular compartment of cancer cells." (PMID 32066374, 2020). "Glutathione-dependent oxidoreductase- CLIC3 is secreted by cancer cell which contributes to tumour micro-environment by promoting angiogenesis and tumour cell invasion." (PMID 32139710, 2020). "In this respect, the recent finding on the contribution of glutathione-dependent oxidoreductase activity of CLIC3 in cancer progression provides physiological evidence for the enzymatic abilities of CLIC family." (PMID 31879279, 2020). "As mentioned, CLIC3 regulates the retrieval of LE-expressed MMP14 back to the degradative invadopodia in MDA-MB-231 cancer cells." (PMID 31439888, 2019). "CLIC3 promotes migration and invasion of cancer cells by facilitating the functions of MT1-MMP (MMP14)." (PMID 30165855, 2018). "The correlation of Rab25/CLIC3 expression and clinical outcome in different types of cancer has to be investigated." (PMID 28969096, 2017). "Next, we assessed the requirement of TGM2 in extracellular CLIC3 ability to promote cancer cell invasion." (PMID 28198360, 2017). "Secreted CLIC3 promotes invasive behaviour of endothelial cells to drive angiogenesis and increases invasiveness of cancer cells both in vivo and in 3D cell culture models, and this requires active transglutaminase-2 (TGM2)." (PMID 28198360, 2017). "Here, the authors compare the secretomes of immortalized normal fibroblasts and cancer-derived fibroblast and identify CLIC3 as a driver of cancer progression." (PMID 28198360, 2017). "Taken together, these data indicate that the extracellular pool of CLIC3 is necessary and sufficient to drive the invasiveness of both ECs and cancer cells." (PMID 28198360, 2017).
cancer (continued). "Rab25 directs ligand-bound active α5β1 integrins to late endosomes and lysosomes, where, instead of degradation, the receptors undergo retrograde transport to the plasma membrane at the rear of cancer cells in a CLIC3-dependent pathway." (PMID 25663697, 2015). "This process, which occurs specifically in cancer cells, requires the concerted activities of Rab25 and chloride intracellular channel protein 3 (CLIC3)." (PMID 25663697, 2015). "Further work will be necessary to define other key molecular components of the CLIC3-regulated recycling pathway, and to determine how these can dictate Rab25's capacity to promote or retard cancer progression." (PMID 22197222, 2012). "CLIC3 is known to activated the NLRP3 inflammasome, which can sense different pathogens or danger signals, and its overexpression has beeb linked to immune evasion in cancer cells." (PMID 39295873, 2024). "CLIC3 also acts as a secreted protein that drives angiogenesis and invasiveness of cancer." (PMID 38182571, 2024). "The significant conflict between the functions of Rab25 in promoting or inhibiting cancer progression in different cancer types might be due to the involvement CLIC3, which is needed for RAB25-regulated integrin transport." (PMID 34141705, 2021). "Consistent with previous research results, we observed that the expression of CLIC1, CLIC3, and CLIC5 was increased in cancer tissues; the expression of CLIC1 and CLIC3 was associated with the progression of the tumor; and a lower expression of CLIC1 was associated with better OS in HCC." (PMID 34766585, 2021). "Furthermore, CLIC3 has been recently shown to promote the invasive behavior of cancer cells through its GSH-dependent oxidoreductase activity." (PMID 31879279, 2020). "CLIC3 was expressed in the plasma membrane of cancer cells in the tissue." (PMID 32066374, 2020). "CLIC3 can drive cancer progression through glutathione-dependent oxidoreductase activity." (PMID 31934512, 2020). "Clearly, CLIC3 levels were similarly regulated in stroma and cancer cells." (PMID 28198360, 2017). "Thus, we have identified CLIC3 as a factor that can be released extracellularly by activated fibroblasts and cancer cells." (PMID 28198360, 2017). "One of the hypotheses suggested that the role of Rab25 depends on its ability to induce chloride intracellular channel protein 3 (CLIC3), which is involved in α5β1 integrin trafficking necessary for cancer cell invasion." (PMID 28969096, 2017). "Concordantly, HGS patients with higher levels of CLIC3 in cancer cells had poorer survival." (PMID 28198360, 2017). "To determine whether secreted CLIC3 contributed to cancer cell invasiveness, we incubated MDA-MB-231 cells with conditioned medium from iCAFs in which CLIC3 had been knocked down." (PMID 28198360, 2017). "Similarly, in cancer cells, CLIC3 in the late endosome/lysosome compartment works with Rab25 to facilitate recycling of fibronectin binding integrins from late endosome/lysosome to plasma membrane." (PMID 27113959, 2016). "Because we have found that CLIC3 acts to recycle integrins that have been targeted to late endosomes/lysosomes by the action of Rab25, we wished to evaluate the expression of CLIC3 in cancers thought to be driven by Rab25." (PMID 22197222, 2012). "Moreover, CLIC3 levels dictate metastasis and poor patient survival, thus highlighting the importance of integrin trafficking to cancer progression in vivo." (PMID 22197222, 2012). "Furthermore, CLIC3 and Rab25 work together to promote cancer progression." (PMID 34721733, 2021). "However, the lysosomal integrin beta 1 could be promoted to recycling from late endosomes or lysosomes by Rab25 and CLIC3 to drive cancer progression." (PMID 29707067, 2018). "The finding indicated that CLIC3 might be a potential molecule to promote cancer progression." (PMID 25970782, 2015).
cancer (continued). "This method with fibrin hydrogels was then later adapted by Hernandez-Fernaud to investigate the role of chloride intracellular channel protein 3 (CLIC3), a protein secreted by CAFs and cancer cells." (PMID 40427172, 2025). "Here we have identified a new pathway whereby extracellular CLIC3 cooperates with TGM2 to drive endothelial and cancer cell invasion." (PMID 28198360, 2017). "Taken together, these data indicate that secreted CLIC3 requires the activity of extracellular TGM2 and α5β1 integrin to promote the invasive behaviour of both ECs and cancer cells." (PMID 28198360, 2017). "Analysis of publicly available gene expression data sets indicated higher CLIC3 levels in the stroma of ovarian (GSE40595), oral (GEOD-38517) and colon (GSE35602) carcinoma when compared with stroma of the corresponding normal tissues." (PMID 28198360, 2017). "In the “CLIC3-low” samples, however, expression level of CLIC3 in the cancer tissue was much lower than non-cancer tissue (right)." (PMID 32066374, 2020). "In the CLIC3-high samples, expression level of CLIC3 in the cancer tissue was comparable to that of adjacent non-cancer tissue (left)." (PMID 32066374, 2020). "While our findings concerning CLIC3 in ESCC are different to that observed in MPM, suggests that further functional investigations of the role of CLIC3 in ESCC and other cancers may be warranted." (PMID 32328183, 2020). "The identification of CLIC3 as a regulator of a recycling pathway and as an independent prognostic indicator in PDAC highlights the importance of active integrin trafficking as a potential drive to cancer progression in vivo." (PMID 22197222, 2012). "Finally, to mimic an excess of extracellular CLIC3 in the tumour microenvironment, regardless of its origin (stromal and/or cancer cells), we mixed MCF10DCIS.com cells with Matrigel in the presence and absence of rCLIC3 and injected this subcutaneously into mice." (PMID 28198360, 2017). "Indeed, western blot analysis detected CLIC3 in the ECM produced by CLIC3-expressing MDA-MB-231 and A2780 cancer cells, but not MCF10DCIS.com cells that have low levels of CLIC3." (PMID 28198360, 2017).